DOCK4 (dedicator of cytokinesis 4)
Diseases named in the same sentence as DOCK4 in open-access papers (continued):
Sharing a sentence is not in itself a finding about the gene and the disease.
DOCK4 also shares sentences with these, for which no sentence is quoted: bipolar disorder (3 papers); migraine (2); Alzheimer disease (1); amyotrophic lateral sclerosis (1); cardiovascular disease (1); chronic myeloid leukemia (1); clear cell renal cell carcinoma (1); colon adenocarcinoma (1); colorectal adenoma (1); communication disorder (1); developmental delay (1); ductal carcinomas (1); eating disorder (1); head and neck squamous cell carcinoma (1); Hearing impairment (1); hematological cancers (1); Intellectual disability (1); kidney tumours (1); major depressive disorder (1); mental disorder (1); metastasis (1); myelodysplastic syndrome (1); Pan (1); pituitary tumor (1); sarcoma (1); type 2 diabetes (1); urothelial carcinoma (1); uterine corpus endometrial carcinoma (1).